PER3 (period circadian regulator 3)
Diseases named in the same sentence as PER3 in open-access papers (continued):
Sharing a sentence is not in itself a finding about the gene and the disease.
breast tumor (3 papers, 2011 to 2021). "Combined data of patient samples and cell lines suggest that breast tumors that undergo genetic alterations on chromosome region 1p36 preferentially lose the more common 4 repeat allele, and retain the PER3 5 repeat allele." (PMID 34508103, 2021). "Overall, we obtained PER3 genotypes for, 5931 samples, including, 2420 cases, 2207 controls, and 1304 breast tumor samples from which 329 presented matched blood genotypes derived from a subset of patients included in the case group." (PMID 34508103, 2021).
chronic myeloid leukemia (3 papers, 2010 to 2017). "Disrupted CRY2 and PER2 are associated with non-Hodgkin’s lymphoma and the initiation and/or progression of AML, respectively, and CpG islands of PER3 are highly methylated in all patients with chronic myelogenous leukemia." (PMID 28487473, 2017). "The expression of Per1, Per2, Per3, Cry1, Cry2, and Bmal1 is significantly impaired in both chronic phase and blast crisis of chronic myeloid leukemia (CML) samples compared with those in normal samples." (PMID 20353609, 2010).
Cluster headache (3 papers, 2015 to 2025). A type of headache characterized by repeated attacks of unilateral pain lasting 15 to 180 minutes and associated with local autonomic signs. "Per3 has been associated with cluster headache and dysregulation of circadian rhythm has been associated with migraine." (PMID 30618656, 2018). "Lithium,indicated as a prophylactic treatment for cluster headache has been found to significantly increase the expression of Per2 and Cry1, and reduce the expression of Per3, Cry2, and Bmal1." (PMID 39560176, 2025).
epilepsy (3 papers, 2015 to 2023). A brain disorder characterized by episodes of abnormally increased neuronal discharge resulting in transient episodes of sensory or motor neurological dysfunction, or psychic dysfunction. "In the rat pilocarpine model, epileptic and naïve rats were compared at specific ZT points following the development of spontaneous seizures, with results showing that development of epilepsy is associated with alterations in rhythmic changes of all three period genes (Per1, Per2, and Per3)." (PMID 32714261, 2020). "Interestingly, the circadian clock pathway was enriched in GO analysis, and several circadian clock genes, such as PER2 and PER3, were regarded as epilepsy-related genes, indicative of circadian involvement in epilepsies/seizures." (PMID 36835631, 2023). "Core clock genes including CLOCK, BMAL1, FBXL21, PER1, PER3, CRY1, and NR1D1 do not show evidence of harboring mutations that cause epilepsy in humans." (PMID 32714261, 2020). "Finally, we showed that temporal differences of sampling can change experimental results for Per1, Per3, Bmal1, Cry1 and Cry2, but not for Clock, which was consistently decreased in rats with epilepsy in all comparison to the naive group." (PMID 26473354, 2015).
head and neck squamous cell carcinoma (3 papers, 2016 to 2024). A squamous cell carcinoma that arises from any of the following anatomic sites: lip and oral cavity, nasal cavity, paranasal sinuses, pharynx, larynx, and salivary glands. "Patients with advanced-stage head and neck squamous cell carcinoma exhibited markedly lower levels of PER1, PER2, and PER3 proteins compared to those with early-stage tumors, and higher levels of these proteins were associated with longer overall and recurrence-free survival." (PMID 38813085, 2024).
mental disorder (3 papers, 2019 to 2025). A disease that has its basis in the disruption of mental process. "Per3 variants are associated with altered diurnal preference and mental disorders." (PMID 39894345, 2025).
myopia (3 papers, 2023 to 2025). "The circadian clock gene PER3 and ASMT (whose protein product catalyzes the final step in melatonin synthesis) relate directly to potential circadian dysregulation in myopia, the hypothesis underlying this study." (PMID 39028695, 2024).
ovarian carcinoma (3 papers, 2015 to 2022). A malignant neoplasm originating from the surface ovarian epithelium. "The goal of the current study was to examine single nucleotide polymorphisms (SNPs) in circadian genes BMAL1, CRY2, CSNK1E, NPAS2, PER3, REV1 and TIMELESS and downstream transcription factors KLF10 and SENP3 as predictors of risk of epithelial ovarian cancer (EOC) and histopathologic subtypes." (PMID 26807442, 2015). "We further evaluated the correlations between PER1 and these 10 interacting proteins based on the GEPIA database and found that the expression of PER1 in ovarian cancer was correlated with that of ARNTL, CLOCK, CRY1, CRY2, CSNK1D, CSNK1E, NPAS2, and PER3." (PMID 34220965, 2021).
schizophrenia (3 papers, 2017 to 2022). A major psychotic disorder characterized by abnormalities in the perception or expression of reality. "Various studies reported disturbed circadian rhythms in schizophrenia patients or model systems in connection to PER2 and PER3 expression or gene polymorphisms." (PMID 34954808, 2022). "Indeed, compared with healthy controls, schizophrenia patients presented disruptions in diurnal rhythms of the expression of Per1, Per3, and Npas2, accompanied by a delayed phase in the expression of Per2 and by a decreasing in Per3 and Npas2 expression." (PMID 28468274, 2017). "Another study suggested that Per3 but not Per2 abnormalities were associated with schizophrenia." (PMID 28468274, 2017).
Sleep disturbance (3 papers, 2016 to 2025). An abnormal pattern in the quality, quantity, or characteristics of sleep. "The current study revealed that, in a sample of healthy women with no self-reported sleep dysfunction, relative to the longer allele carriers, the PER3(4/4) allele carriers were at greater risk for transient psychological effects when they reported reduced sleep (≤6 hrs/night)." (PMID 27103936, 2016).
alcohol abuse (2 papers, 2022 to 2023). The use of alcoholic beverages to excess, either on individual occasions ("binge drinking") or as a regular practice. "A similar finding was reported in a study, which also found associations between PER3 gene VNTR polymorphisms afternoon chronotypes and alcohol abuse." (PMID 36981669, 2023).
anxiety disorder (2 papers, 2016 to 2024). A category of psychiatric disorders which are characterized by anxious feelings or fear often accompanied by physical symptoms associated with anxiety. "In particular, we showed that a reduced sleep duration, combined with the PER3(4/4) genotype, was associated with greater mood disturbances and increased state anxiety." (PMID 27103936, 2016). "By elucidating the impact of PER3 gene polymorphism on psychological outcomes, this research contributes to a deeper understanding of the genetic underpinnings of anxiety disorders and may inform personalized approaches to mental health care." (PMID 39759625, 2024).
colitis (2 papers, 2022 to 2025). Inflammation of the colon. "On the contrary, we found that in colorectal stromal cells, colitis was associated with decreases in the mRNA levels of Arntl, Clock, Cry1, Cry2, Per2, Per3, Nr1d1, Npas2, and BBR restored the expression of these genes except Per2." (PMID 36528592, 2022). "We also compared the expression of several key circadian genes including Arntl, Clock, Cry1, Cry2, Per1, Per2, Per3, Nr1d1, and Npas2 in colon samples collected at 03, 09, 15, and 21 of normal mice, colitis mice, normal mice receiving BBR, and colitis mice receiving BBR." (PMID 36528592, 2022).
Erythema (2 papers, 2022 to 2025). Redness of the skin, caused by hyperemia of the capillaries in the lower layers of the skin. "Significant predictors for erythema included BMI, radiation dose and PER3 genotype (OR 1.27(95%CI 1.03-1.56); P < 0.03)." (PMID 36130474, 2022).
gastric cancer (2 papers, 2020 to 2021). A primary or metastatic malignant neoplasm involving the stomach. "Therefore, further studies are necessary to fully address the functional role of PER3 in gastric cancer or precancerous lesions and whether such a role is exerted through the Circadian Rhythm Pathway." (PMID 34721627, 2021).
multiple sclerosis (2 papers, 2022 to 2024). A progressive autoimmune disorder affecting the central nervous system resulting in demyelination. "A variable number tandem-repeat (VNTR) polymorphism in the PER3 gene related with immune response, circadian rhythm phenotypes and homeostatic regulation of sleep, might accelerate the disease course in Multiple Sclerosis (MS) patients by disrupting circadian cycle of sleep." (PMID 36614124, 2022).
obstructive sleep apnea (2 papers, 2020 to 2023). "Similarly, the combined downregulation in the expressions of CRY1 and PER3 at midnight predicted the severity of the disease in patients with obstructive sleep apnea/hypopnea syndrome." (PMID 32823749, 2020). "In a separate study involving individuals with obstructive sleep apnea (OSA), it was noted that the transcription of BMAL1, CLOCK, and CRY2 was irregular, and the levels of CRY1 and PER3 significantly decreased at midnight." (PMID 38067152, 2023).
osteosarcoma (2 papers, 2021 to 2024). A usually aggressive malignant bone-forming mesenchymal neoplasm, predominantly affecting adolescents and young adults. "Herein, the same core circadian clock genes that are rhythmically controlled by CRY1 in osteosarcoma cells are also bound by CRY1 in PCa (i.e., CRY1, CRY2, PER2, and PER3) showing concordance of binding across models regardless of circadian synchronization." (PMID 33452241, 2021).
Sepsis (2 papers, 2025). Sepsis is defined as life-threatening organ dysfunction caused by a dysregulated host response to infection. "As clock genes, PER2, PER3, and CRY1 may be markers of sepsis severity." (PMID 40362233, 2025).
status epilepticus (2 papers, 2018 to 2020). Status epilepticus is defined as a continuous seizure lasting more than 30 min, or two or more seizures without full recovery of consciousness between any of them. "Only the expression of Per3 was downregulated 24 h after the induction of status epilepticus." (PMID 32111960, 2020). "In this study, we systematically evaluated the temporal expression of seven core circadian transcripts (Bmal1, Clock, Cry1, Cry2, Per1, Per2, and Per3) and the spontaneous locomotor activity (SLA) in post-status epilepticus (SE) model of mTLE." (PMID 30116220, 2018).
acute myeloid leukemia (1 paper, 2021). Acute myeloid leukemia (AML) is a group of neoplasms arising from precursor cells committed to the myeloid cell-line differentiation. "In acute myeloid leukemia (AML), PER2, PER3, and CRY levels are reduced due to reduced expression of CCAAT/enhancer-binding proteins (C/EBPs), while BMAL1, CLOCK, and PER1 levels increase." (PMID 34966277, 2021).
adenoma (1 paper, 2015). A neoplasm arising from the epithelium. "The meta-analysis indicated that the strength of association between PER3 genotype and adenoma status was generally consistent with the main analysis and the results were not strongly impacted by heterogeneity between the sites." (PMID 25501848, 2015). "Nonetheless, the lower bound of the confidence intervals suggest an increased risk for adenoma formation of at least ~40% among homozygous 5-repeat PER3 variants." (PMID 25501848, 2015). "Adenoma cases were ~2–5 times more likely to possess the 5-repeat PER3 length polymorphism compared to controls." (PMID 25501848, 2015). "In conclusion, the present study indicates that individuals with the 5-repeat PER3 length polymorphism may be more susceptible to adenoma formation." (PMID 25501848, 2015). "This exploratory case-control study was the first to test the hypothesis that the 5-repeat PER3 VNTR sequence is associated with increased odds of adenoma formation." (PMID 25501848, 2015). "Therefore, this exploratory study tested the hypothesis that adenoma cases are hetero- or homozygous for the 5-repeat PER3 variant relative to adenoma-free controls." (PMID 25501848, 2015). "Data for PER1, PER2 and PER3 expression in adenomas relative to normal tissue were retrieved from the Oncomine microarray database." (PMID 25501848, 2015). "A statistically significant reduction in PER3 expression was observed in adenomas relative to normal tissue among each of the available data sets; similar differences were noted for PER1, and to a lesser extent PER2 expression." (PMID 25501848, 2015). "Further interrogation of interrelationships between the PER3 VNTR and genetic or epigenetic pathways that may facilitate adenoma risk, such as changes in the expression of clock-controlled, cancer-related genes, is recommended." (PMID 25501848, 2015). "The role of PER3 or other clock genes in human adenoma formation has yet to be examined in detail." (PMID 25501848, 2015). "Further elucidation of the PER3 VNTR genotype in relation to circadian rhythm or clock gene dysregulation may lead to development of novel, modifiable targets for adenoma and CRC prevention." (PMID 25501848, 2015).
afibrinogenemia (1 paper, 2022). "As to OMIM diseases, PER3 was related to congenital dysfibrinogenemia and congenital afibrinogenemia." (PMID 36385012, 2022).
attention deficit-hyperactivity disorder (1 paper, 2022). A disorder characterized by a marked pattern of inattention and/or hyperactivity-impulsivity that is inconsistent with developmental level and clearly interferes with functioning in at least two settings (e.g. at home and at school). "PER3 in particular was linked to attention-deficit hyperactivity disorder, which would comply with a hyperactivity disorder model of FP as proposed by Kjaer." (PMID 34954808, 2022).
bipolar I disorder (1 paper, 2024). A bipolar disorder that is characterized by at least one manic or mixed episode. "In the present study, the Kaplan-Meier analysis was conducted to investigate the association of PER3 VNTR genotypes with age of onset in an independent sample of 45 patients diagnosed with bipolar I disorder." (PMID 38992306, 2024). "With the present study, we aimed to confirm the suggested association of PER3 VNTR genotypes with age of onset in an independent sample of 45 German patients diagnosed with bipolar I disorder." (PMID 38992306, 2024). "The research conducted by Benedetti investigated the impact of PER3 VNTR polymorphisms on the age of onset in a group of 99 patients diagnosed with bipolar I disorder through a Kaplan-Meyer analysis." (PMID 38992306, 2024). "In this study, we aimed to investigate these associations of PER3 VNTR genotypes with age of onset in a homogenous sample of German patients with bipolar I disorder through Kaplan-Meier curves." (PMID 38992306, 2024).
brain tumor (1 paper, 2024). "Genes including CRY2, NR1D2, and PER3, were found to have a positive correlation with high overall survival (OS) and disease-free survival (DFS) in brain tumor patients." (PMID 39043735, 2024).
chronic lung disease (1 paper, 2021). According to the definitions of the American and British Thoracic Societies, including pulmonary functional tests, X-rays, and CT scans for items such as fibrosis, bronchiectasis, bullae, emphysema, nodular or lymphomatous abnormalities. "Some of these genes, such as VAMP3, LGR5, PER3, and SDC1, were found to be involved in the different physiological functions of lung and chronic lung disease." (PMID 33407823, 2021).
colon adenocarcinoma (1 paper, 2021). "Compared to normal skin, patients with skin cutaneous melanoma (SKCM) present significant down-regulation in the expression of BMAL1, CRY1, CRY2, PER1, PER2, and PER3, and higher expression of CLOCK, a similar pattern was also observed in patients with colon adenocarcinoma (COAD)." (PMID 34966277, 2021).
dementia (1 paper, 2017). Loss of intellectual abilities interfering with an individual's social and occupational functions. "Cell-enriched hair roots obtained from old-old dementia patients (subjects A, C, D and E) were infected with an adenovirus carrying Per3-luc, and bioluminescence rhythms were monitored in real time." (PMID 28755004, 2017).
endometrial cancer (1 paper, 2025). Primary or metastatic malignant neoplasm involving the endometrium (mucous membrane that lines the endometrial cavity). "Additionally, they have observed that Clock and PER3 exhibit reduced expression in endometrial cancer tissues." (PMID 39944833, 2025).
fibromyalgia (1 paper, 2024). A chronic disorder of unknown etiology characterized by pain, stiffness, and tenderness in the muscles of neck, shoulders, back, hips, arms, and legs. "The PER3 gene polymorphism was analyzed across three genotypes: 4/4, 4/5, and 5/5, with significant associations observed between genotype distributions and fibromyalgia syndrome (FMS)." (PMID 39759625, 2024). "Additionally, the PER3 VNTR genotype exhibited associations with both the fibromyalgia impact questionnaire-revised (FIQR) and visual analog scale (VAS) scores, indicating its potential role in influencing disease severity and symptomatology." (PMID 39759625, 2024).
gastric ulcer (1 paper, 2020). An ulcerated lesion in the mucosal surface of the stomach. "Therefore, per3 might be one of the regulatory genes associated with gastric ulcers." (PMID 32148538, 2020).
glioblastoma (1 paper, 2024). The most malignant astrocytic tumor (WHO grade IV). "The AUC values were above 0.9, indicating that the diagnostic effect of PER3 in predicting the outcome was consistent with the common prognostic biomarkers of glioblastoma." (PMID 39771050, 2024). "Consequently, the aim of this study is to investigate the diagnostic and prognostic role of PER3 in glioblastoma multiforme (GBM) and to provide a new scientific basis for the carcinogenicity of DEHP." (PMID 39771050, 2024). "In glioblastoma tissues, patients with high tumor progression exhibited lower levels of PER3." (PMID 39771050, 2024). "The analysis of the K-M survival curve revealed that patients with glioblastoma multiforme who had low PER3 expression levels had significantly lower overall survival, disease-specific survival, and progression-free interval compared to those with high levels of PER3 expression." (PMID 39771050, 2024). "The GEO database screening of glioblastoma cases also revealed a low expression of the PER3 gene." (PMID 39771050, 2024). "Furthermore, PER3 expression was significantly reduced in glioblastoma tissues from the GSE29458, GSE22866, and GSE14805 datasets compared to the corresponding controls." (PMID 39771050, 2024). "Both PER3 and EGFR are potential targets for glioblastoma-targeted therapy." (PMID 39771050, 2024).
Hepatic steatosis (1 paper, 2025). Steatosis is a term used to denote lipid accumulation within hepatocytes. "Furthermore, clock genes including hepatic Per3, Reverbα, and Rorc were significantly altered in the SJL group at ZT12, suggesting that circadian rhythm may also participate in SJL-induced hepatic steatosis." (PMID 40462123, 2025).
heroin dependence (1 paper, 2024). Physical and psychological dependence on the drug heroin. "For example, PER3 variations have been linked to stress and addiction in mice, as well as heroin dependence in a Han Chinese population." (PMID 39766481, 2024).
Hypertension (1 paper, 2020). The presence of chronic increased pressure in the systemic arterial system. "In contrast, gene expression profiling of Spontaneously Hypertensive (SHR) rats, a genetic model of hypertension, demonstrated decreased expression of Bmal1 and Npas2, while Per1, Per2, Per3, Cry1, Cry2, Bhlhe41 and Csnk1D were all upregulated compared to naïve WKY controls." (PMID 33127986, 2020).
hypertrophy (1 paper, 2022). Hypertrophy is the increase in the volume of an organ or tissue due to the enlargement of its component cells. "Genes coexpressed with PER3 were correlated with “Development_Gastrin in cell growth and proliferation”, “NF-AT signaling in cardiac hypertrophy”, and “Immune response_Gastrin in inflammatory response”." (PMID 36385012, 2022).